SFTPA1 (surfactant protein A1)
Description:
In presence of calcium ions, it binds to surfactant phospholipids and contributes to lower the surface tension at the air-liquid interface in the alveoli of the mammalian lung and is essential for normal respiration. Enhances the expression of MYO18A/SP-R210 on alveolar macrophages (By similarity). (Microbial infection) Recognition of M.tuberculosis by dendritic cells may occur partially via this molecule. Can recognize, bind, and opsonize pathogens to enhance their elimination by alveolar macrophages. (Microbial infection) Binds M.pneumoniae CARDS toxin, serves as one receptor for this pathogen. When SFTPA1 is down-regulated by siRNA, less toxin binds to human cells and less vacuolization (a symptom of M.pneumoniae infection) is seen.
Synonyms: PSP-A; PSPA; SP-A; SP-A1; COLEC4; SFTP1; SFTPA1B; ILD1; SP-A1 beta; SP-A1 delta; SP-A1 epsilon; SP-A1 gamma; SPA; SPA1
Tractability: Antibody: UniProt places it where antibodies can reach, with high confidence; its Gene Ontology location is reachable by antibodies, with high confidence; UniProt predicts a signal peptide or a membrane-spanning region.
Gene: Protein-coding gene on chromosome 10 (79,610,412 to 79,616,115, forward strand). Ensembl gene ENSG00000122852.
Subcellular location: Secreted; Secreted, extracellular space, extracellular matrix; Secreted, extracellular space, surface film
Pathways (Reactome):
Immune System: Regulation of TLR by endogenous ligand; Toll Like Receptor 4 (TLR4) Cascade; Toll Like Receptor TLR1:TLR2 Cascade
Disease: Defective CSF2RA causes SMDP4; Defective CSF2RB causes SMDP5
Cell-Cell communication: Signal regulatory protein family interactions
Metabolism of proteins: Surfactant metabolism
Gene Ontology:
Molecular function: protein binding; lipid transporter activity
Biological process: opsonization
Cellular component: extracellular region; clathrin-coated endocytic vesicle; endoplasmic reticulum membrane; lamellar body; multivesicular body
Genetic constraint (gnomAD): Loss-of-function variants: 14 observed, 21.34 expected, observed/expected ratio (o/e) 0.66, 90% interval 0.43 to 1.03. The upper end of that interval is the gene's LOEUF score, 1.03, which puts it in group 4 of 6, group 1 being the genes least tolerant of losing a copy. Missense variants: 259 observed, 316.15 expected, observed/expected ratio (o/e) 0.82, 90% interval 0.74 to 0.91. Synonymous variants: 101 observed, 115.89 expected, observed/expected ratio (o/e) 0.87, 90% interval 0.74 to 1.03.
Gene-disease validity (ClinGen):
ClinGen rates the evidence that SFTPA1 causes each of these diseases.
interstitial lung disease 1 (autosomal dominant): Moderate. An interstitial lung disease in which the cause of the disease is a variation in the SFTPA1 gene.
Homologues: Orthologues: chimpanzee SFTPA1 (99% identical), macaque SFTPA1 (92% identical), pig SFTPA1 (76% identical), rabbit SFTPA1 (75% identical), mouse Sftpa1 (71% identical), rat Sftpa1 (71% identical), guinea pig Sftpa1 (70% identical), tropical clawed frog sftpa (49% identical). Paralogues in human: SFTPA2 (97% identical), SFTPD (40% identical), COLEC10 (27% identical), COLEC11 (27% identical).
Diseases named in the same sentence as SFTPA1 in open-access papers:
SFTPA1 is named in the same sentence as 44 diseases in open-access papers, as found by Europe PMC text mining. Sharing a sentence is not in itself a finding about the gene and the disease. The quoted sentences say what the papers report.
lung carcinoma (19 papers, 2015 to 2026). "In instances where an association with ILD/PF and lung cancer was reported, all patients with a positive molecular diagnosis exhibited SFTPA1 or SFTPA2 variants (n = 4)." (PMID 41041870, 2026). "Lung cancer develops in up to one third of patients carrying SFTPA1 and SFTPA2 germline mutations, suggesting an increased risk of lung cancer." (PMID 37893169, 2023). "SFTPA1 disruption can cause several acute or chronic lung diseases, including lung cancer." (PMID 34181042, 2022). "However, little research has been performed to associate SFTPA1 with immune cell infiltration and the response to immunotherapy in lung cancer." (PMID 34181042, 2022). "It has been reported that SFTPA1 mutation was associated with familial idiopathic interstitial pneumonia and lung cancer, which shed light on the key role of SFTPA1 in the pathogenesis of several chronic respiratory diseases, especially in lung cancer." (PMID 29152081, 2017). "SFTPA1 variant carriers are at increased risk of inherited lung disease, and this gene may be a viable prognostic biomarker since it is connected to immune cell infiltration and the effectiveness of immunotherapy in lung cancer." (PMID 38495669, 2024). "Pathogenic variants in SFTPA1 and SFTPA2 are also associated with lung malignancy, like in this case, with the risk of lung cancer in this group estimated to be as high as 36% as compared to 13% for individuals with IPF." (PMID 38461429, 2024). "Pathogenic mutations in SFTPA1 and SFTPA2 have been mainly linked to FPF cases and they usually also associate with lung cancer in adult patients." (PMID 37181377, 2023). "Mutations in SFTPA2 and SFTPA1 have been reported only in adults and they are considered a recognized cause of IPF and lung cancer." (PMID 37181377, 2023). "According to the Oncomine online database, the downregulation of SFTPA1 expression was observed in the brain and central nervous system cancer, breast cancer, and lung cancer, whereas it was up-regulated in prostate cancer." (PMID 34181042, 2022). "Consistent with the results in normal human tissues, SFTPA1 mRNA was primarily expressed in lung cancer." (PMID 34181042, 2022). "To identify the predictive power of SFTPA1 as an immunotherapy biomarker, we collected the tumor tissues of 12 lung cancer patients before treatment with a Pembrolizumab-based regimen." (PMID 34181042, 2022). "Our findings demonstrate that SFTPA1 was up-regulated in the lung cancer tissues and was involved in the development and progression of lung adenocarcinoma through the regulation of various immune-related pathways." (PMID 34181042, 2022). "A subsequent DNA CpG methylation profiling of the SFTPA1 gene promoter identified two CpG SFTPA1 sites (SFTPA1_370 and SFTPA1_1080) to be hypomethylated in lung cancer (adenocarcinoma and squamous cell carcinoma)." (PMID 34917085, 2021). "Among the six LUAD-SDGs, surfactant protein A including SFTPA1 and SFTPA2 were reported closely associated with lung cancer." (PMID 29152081, 2017). "Although PF is known to increase the risk of lung cancer, this association should strongly recommend a molecular screening for SRG, especially SFTPA1 and SFTPA2, which have recently been shown to be associated with a high risk of lung cancer, particularly in smokers." (PMID 41041870, 2026). "The only marker that appeared specifically expressed in lung cancer tissue was SFTPA1." (PMID 37264016, 2023). "Moreover, a previous study reported that SFTPA1 inhibited lung cancer progression by controlling M1 macrophage polarization in mice models." (PMID 34181042, 2022). "Specifically for lung cancer, the highest expression level was observed in the alveolar (gene annotation: CLDN18, SFTPA1, SFTPA2, SFTPC) cell population, and erythroblasts (gene annotation not available) also increased their expression." (PMID 35631632, 2022).
lung carcinoma (continued). "A lung cancer-specific gene signature, containing SFTPA1 and SFTPA2 genes, accurately distinguished lung cancer from other cancer samples, the predictive accuracy of LOOCV for TCGA and GSE5364 data were 95.68% and 100%, respectively." (PMID 26292924, 2015). "The positive SFTPA1 expression group exhibited a higher partial response (PR) rate than the negative group in all lung cancer patients (positive vs negative; PR: 67% vs 50%), and a lower progressive disease (PD) rate (0% vs 17%)." (PMID 34181042, 2022). "We categorized the 12 lung cancer patients into SFTPA1 positive/negative expression groups according to SFTPA1 protein expression." (PMID 34181042, 2022). "The differential regulation of the methylation status of specific CpGs in SFTPA1 and SFTPA2 maybe one of the epigenetic processes that does not only apply to lung cancer but also to other health states." (PMID 34917085, 2021). "In addition, they found a lung cancer-specific gene signature, containing SFTPA1 and SFTPA2 genes, that was able to distinguish lung cancer from the other cancers." (PMID 34570764, 2021).
lung adenocarcinoma (11 papers, 2019 to 2025). A carcinoma that arises from the lung and is characterized by the presence of malignant glandular epithelial cells. "High SFTPA1 mRNA expression was associated with a favorable prognosis through a survival analysis in lung adenocarcinoma (LUAD) samples from TCGA." (PMID 34181042, 2022). "This subset of patients is distinguishable clinically by earlier-onset disease in young adults associated with surfactant protein C (SFTPC) mutations and a history of lung adenocarcinoma being associated with surfactant protein A1 and A2 (SFTPA1 and SFTPA2) mutations." (PMID 35532056, 2022). "Mutations in surfactant protein genes SFTPA1 and SFTPA2 in lung adenocarcinoma impair protein secretion, induce endoplasmic reticulum stress and apoptosis, fostering co-occurrence of PF and LC." (PMID 40625354, 2025). "SFTPA1 and SFTPA2 (surfactant proteins A1 and A2): Variants in these nearly identical genes are associated with both PPF and lung adenocarcinoma." (PMID 41465275, 2025). "Among the 23 significantly upregulated genes in the durable disease control group, SFTPA1 was reported as a potential predictive biomarker for immunotherapy for lung adenocarcinoma." (PMID 38339307, 2024). "Considering that the results were consistent with the previous studies in LUAD, we focused on the pathological type of lung adenocarcinoma to investigate the molecular mechanisms of SFTPA1." (PMID 34181042, 2022). "A total of 513 lung adenocarcinoma samples from TCGA database were divided into two groups based on the median SFTPA1 expression data, and ic2.cp.kegg.v7.0.symbols.gmt was used as the background gene set." (PMID 34181042, 2022). "Mutations in the genes encoding SP–A, SFTPA1 and SFTPA2, are associated with interstitial lung disease and increased susceptibility to adenocarcinoma of the lung." (PMID 32493486, 2020). "Among the top 10 genes with a high average ΔPCC in lung adenocarcinoma (LUAD), several genes such as CLDN18, ADAMTS8, PECAM1 and SFTPA1 have been known to be associated with LUAD in previous studies." (PMID 32854705, 2020). "Collectively, our study extends the expression profile and potential regulatory pathways of SFTPA1 and may provide a potential biomarker for establishing novel preventive and therapeutic strategies for lung adenocarcinoma." (PMID 34181042, 2022). "Our findings indicate that SFTPA1 may be a predictor of favorable prognosis and immunotherapeutic response for patients with lung adenocarcinoma." (PMID 34181042, 2022). "Finally, SFTPA1, PLXNB3, BIRC5, CBLC, and ACVRL1 were screened out based on the intersection between the top 10 differentially expressed genes in lung adenocarcinoma (LUAD) and lung squamous cell carcinoma (LUSC)." (PMID 34181042, 2022). "Unlike lung adenocarcinoma, high SFTPA1 expression was associated with an inactive immune microenvironment in LUSC, which may partially explain the different prognostic implications of SFTPA1." (PMID 34181042, 2022).
pulmonary fibrosis (11 papers, 2014 to 2025). Chronic progressive interstitial lung disorder characterized by the replacement of the lung tissue by connective tissue, leading to progressive dyspnea, respiratory failure, or right heart failure. "Moreover, the mutation of homozygous SFTPA1 drives the necroptosis of type II alveolar epithelial cells in idiopathic pulmonary fibrosis." (PMID 38020922, 2023). "Constructed a targeting vector with a mutation in surfactant protein A1 or put a mutation in surfactant protein A1 in the CRISPR/Cas9 to established surfactant protein A1-knock in mice, the homozygous mutant mice spontaneously developed pulmonary fibrosis." (PMID 38007420, 2023). "Lately, mutations in the SFTPA1 and SFTPA2 have been associated with familiar pulmonary fibrosis and rarely with sporadic IPF." (PMID 37893169, 2023). "Mutations in genes encoding SP-A, SFTPA1 and SFTPA2 have been so far associated with familiar pulmonary fibrosis and rarely with sporadic IPF." (PMID 37893169, 2023). "Mutation in SFTPA1 resulted in IPF in a consanguineous Japanese family, and SFTPA1 knock-in (Sftpa1-KI) mice spontaneously developed pulmonary fibrosis with increased necroptosis derived by c-Jun N-terminal kinase (JNK)-mediated upregulation of RIPK3 in AEC2s." (PMID 34594225, 2021). "JNK inhibition ameliorated pulmonary fibrosis in Sftpa1-KI mice, but it was blocked with RIPK3 overexpression." (PMID 34594225, 2021). "Mutations in SFTPA1 and SFTPA2 are associated with idiopathic pulmonary fibrosis, and (along with SFTPD) play an essential role in surfactant homeostasis and in the defense against respiratory pathogens." (PMID 25961286, 2015). "Mutations of surfactant-associated genes, including SFTPA1 (location: 10q22.3), SFTPA2 (10q22.3), SFTPC (8p21.3), SFTPB (2p11.2), ABCA3 (16p13.3) and NKX2.1 (14q13.3)), are the second most frequent forms of pulmonary fibrosis, approximately occurring in 1–5% of familial cases." (PMID 37893169, 2023).
interstitial lung disease (7 papers, 2014 to 2025). A diverse group of lung diseases that affect the lung parenchyma. "Previous studies have shown that the disruption of SFTPA1 homeostasis could induce both acute and chronic lung diseases, including respiratory distress syndrome and interstitial lung diseases." (PMID 34181042, 2022).
idiopathic pulmonary fibrosis (6 papers, 2014 to 2025). Idiopathic pulmonary fibrosis (IPF) is a nonneoplastic pulmonary disease that is characterized by the formation of scar tissue within the lungs in the absence of any known cause. "Sequence variants in genes for surfactant proteins (SFTPC, SFTPA1, SFTPA2, ABCA3), polymorphisms in MUC5B or TOLLIP, and mutations in telomere genes (TERT, TERC, PARN, and RTEL1) are associated with an increased risk of idiopathic pulmonary fibrosis (IPF)." (PMID 36864460, 2023). "SFTPA1 promotes increased necroptosis of type II alveolar epithelial cells through the IRE1α-JNK axis and the progression of idiopathic pulmonary fibrosis (IPF)." (PMID 40362609, 2025).
lung disease (5 papers, 2018 to 2025). "Several genetic variants have been identified for SFTPA1, SFTPA2, SFTPB, SFTPC, and SFTPD that are associated with pulmonary diseases." (PMID 33469544, 2020). "In this study, we report the novel association of polymorphisms in the human surfactant protein genes SFTPA1, SFTPA2, and their associated haplotypes, with the odds of developing ROP while controlling for GA, oxygen exposure and lung disease in preterm infants." (PMID 41102472, 2025). "Unlike in rodents that have a single gene encoding surfactant protein A (SP-A), in humans SP-A consists of SP-A1 and SP-A2 encoded by SFTPA1 and SFTPA2, respectively; each gene has been identified with several genetic variants, and these have been shown to associate with several pulmonary diseases." (PMID 30333828, 2018). "A number of intergenic interactions that all include SNPs of SFTPB as well as a single intragenic SFTPA1 and SFTPA2 interaction are likely to be markers for mild and moderate/severe pulmonary disease in CF, respectively." (PMID 30333828, 2018).
chronic lung disease (4 papers, 2022 to 2025). According to the definitions of the American and British Thoracic Societies, including pulmonary functional tests, X-rays, and CT scans for items such as fibrosis, bronchiectasis, bullae, emphysema, nodular or lymphomatous abnormalities. "Interruption of SFTPA1 can lead to a variety of acute or chronic lung diseases." (PMID 38887981, 2024).
COVID-19 (4 papers, 2020 to 2025). A disease caused by infection with severe acute respiratory syndrome coronavirus 2. "The mean expression values for the studied genes across the groups were as follows: SFTPA1 showed levels of 0.0461 ± 0.0270 in the asymptomatic COVID-19-positive patient group, 0.0271 ± 0.0069 in the mild group, and 0.0199 ± 0.0136 in the severe group." (PMID 40647689, 2025). "This study aimed to elucidate the effect of COVID-19 on the lung’s surface tension regulatory system by examining the expression of surfactant protein genes (SFTPA1, SFTPA2, SFTPB, SFTPC, and SFTPD) across different disease severity groups." (PMID 40647689, 2025). "In this study, we compared the expression of SFTPA1, SFTPA2, SFTPB, SFTPC, and SFTPD in blood among asymptomatic, mild, and severe COVID-19 patients to identify patterns related to disease severity." (PMID 40647689, 2025).
respiratory distress syndrome (4 papers, 2007 to 2024). "Additional polymorphisms within SFTPA1 and SFTPA2, have been linked to respiratory distress syndrome in infants, severe RSV bronchiolitis, and otitis media." (PMID 33617569, 2021). "Polymorphisms within SFTPA1 and SFTPA2, two functional, highly homologous SFTPA genes have been linked to respiratory distress syndrome in infants, severe RSV bronchiolitis, and otitis media." (PMID 17407567, 2007).
acute respiratory failure (3 papers, 2020 to 2023). Life-threatening respiratory failure that develops rapidly. "In another study comparing children with acute respiratory failure and healthy newborn controls, SNPs in SFTPA1, SFTPA2, and SFTPC were associated with acute respiratory failure and pulmonary dysfunction after hospital discharge." (PMID 35913450, 2022). "Conversely, the same SFTPA1 intragenic SNP interaction (rs1059047 x rs1136450 x rs1136451) with dominant effects of each SNP was associated with decreased risk of pediatric acute respiratory failure." (PMID 33469544, 2020).
asthma (2 papers, 2007 to 2025). "Unadjusted associations between SNPs from surfactant protein A alleles (SFTPA1,SFTPA2) and respiratory symptomsa during the first year of life for white infants at risk for developing asthma." (PMID 17407567, 2007). "In the present study, we used a candidate gene approach to investigate whether polymorphisms within the SFTPA1 and SFTPA2 genes were associated with wheeze and persistent cough during the first year of life among a prospective birth cohort at risk for developing asthma." (PMID 17407567, 2007).
atherosclerosis (1 paper, 2024). A disease characterized by the build-up of fatty material and calcium deposition in the arterial wall resulting in partial or complete occlusion of the arterial lumen. "Finally, miR-199b-5p upregulation was predicted to lead to the activation of HbA1c (HBA1/HBA2) through the inhibition of surfactant protein A1 (SFTPA1), thus resulting in a predicted association with enhanced atherosclerosis progression." (PMID 39125657, 2024).
chorioamnionitis (1 paper, 2021). A morphologic finding indicating inflammation of the fetal sac membranes. "Furthermore, the concern for infection in the setting of prematurity and chorioamnionitis sets up the SFTPA1 and SFTPA2 gene products, SP-A1 and SP-A2, as very important molecules for the first line of defense and regulation of various processes of the alveolar macrophage." (PMID 34671583, 2021).
idiopathic interstitial pneumonia (1 paper, 2019). A class of diffuse lung diseases that typically affect the pulmonary interstitium, although some also have a component affecting the airways (for instance, Cryptogenic organizing pneumonitis). "Here, we report a novel, rare SFTPA1 variant in a family with idiopathic interstitial pneumonia (IIP)." (PMID 30854216, 2019).
lung tumor (1 paper, 2015). "The expression levels of SFTPA1 and SFTPA2 were much higher in lung tissue samples than in any other tissue samples, moreover, these two genes were strikingly down-regulated in lung tumor tissues as compared to the adjacent nontumor tissues." (PMID 26292924, 2015).